PIK3CA (phosphatidylinositol-4,5-bisphosphate 3-kinase catalytic subunit alpha)
Diseases named in the same sentence as PIK3CA in open-access papers (continued):
Sharing a sentence is not in itself a finding about the gene and the disease.
breast cancer (continued). "PIK3CA is one of the most frequently mutated genes in human breast cancer with distinct subtypes, implying the contribution of the PIK3CA mutation to breast cancer heterogeneity." (PMID 31013830, 2019). "Taken together, these data demonstrate that breast cancer cells with activating mutations in PIK3CA are selectively sensitive to RNMT inhibition." (PMID 30991934, 2019). "In this study, we directly compared PIK3CA hotspot mutations (E545K, H1047R) in EpCAM‐positive CTCs and paired plasma‐ctDNA in breast cancer (BrCa)." (PMID 31254443, 2019). "We found that cells with activating mutations in PIK3CA, which are present in around 35% of breast cancers, exhibit enhanced dependency on RNMT for proliferation." (PMID 30991934, 2019). "Evidence includes a study demonstrating that PDK1-mediated SGK3 activation was critical for anchorage-independent growth in a subset of PIK3CA (the gene encoding for p110α) mutant breast cancer cell lines with minimal Akt activation." (PMID 31088502, 2019). "Our direct comparison study revealed for the first time that in early breast cancer, PIK3CA hotspot mutations are present in CTCs at a higher percentage before than after treatment, when compared to paired plasma‐ctDNA samples." (PMID 31254443, 2019). "The dysregulation of the PI3K/AKT pathway has been demonstrated in different solid tumors including breast cancer, and it has been suggested that this dysregulation is associated with the increased mutations in pathway genes PIK3CA and AKT1." (PMID 30682127, 2019). "Several retrospective and prospective studies have evaluated the prognostic and predictive value of PIK3CA mutations in breast cancer tumors." (PMID 31404155, 2019). "We conducted a phase II trial with an allosteric AKT inhibitor MK-2206 in patients with advanced breast cancer who had tumors with PIK3CA/AKT1 mutations and/or PTEN loss/mutation." (PMID 31277699, 2019). "This mutation occurs in about 30% of human breast cancers, where it leads to gain-of-function mutations in gene PIK3CA that activate the PI3K-AKT-signaling pathway constantly, thereby uncoupling the EGFR response from AKT signaling." (PMID 31438847, 2019). "Seven belonged to a set of genes upregulated in PIK3CA-mutated ERalpha-positive breast cancer cells." (PMID 31101122, 2019). "The concordance of PIK3CA mutations between CTCs and ctDNA was relatively poor in early breast cancer (48.2%) and higher in the metastatic setting (66.6%)." (PMID 31254443, 2019). "In stage I of the study, we observed a confirmed partial response in a patient with a breast cancer bearing a PIK3CA mutation." (PMID 31277699, 2019). "In two patients, we found two mutations (MAP3K1 L380fs and PIK3CA I391M, respectively) present in the mastopathy as well as in the subsequent breast cancer." (PMID 31396514, 2019). "Apelisib greatly improved PFS in patients when given in combination with fulvestrant to patients with endocrine-refractory, advanced ER+ breast cancer harboring PIK3CA mutations." (PMID 31106278, 2019). "In one case, a MAP3K1 L380fs mutation was present in the mastopathy as well as in the tumor tissue, and in another case, a PIK3CA I391M mutation was present in the mastopathy as well as in the subsequent breast cancer." (PMID 31396514, 2019).
breast cancer (continued). "In our case series of patients who underwent repeat hepatectomies for breast cancer liver metastases, PIK3CA hotspot mutations were frequently observed in most of the nodules for multinodular tumors and persist along with the liver metastases recurrence." (PMID 30795751, 2019). "In regard to mutations in PIK3CA, mutations were reported in 27% of breast cancer cases in Brazil and in 15.7% of HER2-amplified and triple negative non-metastatic cases in Peru." (PMID 30792813, 2019). "In a very short span of time, several mutations in PIK3CA were discovered, making it the most frequently mutated oncogene in breast cancer." (PMID 31905960, 2019). "The most frequently observed mutations occurred within the coding region of PIK3CA (6 out of 18 mutations detected) for breast cancer and EGFR (40 out of 57 mutations detected) for NSCLC specimens." (PMID 31296838, 2019). "It has been shown that breast cancer cells that harbor mutated PTEN or PIK3CA were sensitive to MK-220625." (PMID 30962488, 2019). "In conclusion, PIK3CA mutations are frequently observed in breast cancer liver metastases and persist over time." (PMID 30795751, 2019). "The differential activity of TFs associated to mutant PIK3CA in isogenic breast cancer cell lines was revealed by comparing the phospho (p)-AKT and p-S6K levels." (PMID 35582587, 2019). "In conclusion, MK-2206 monotherapy had limited clinical activity in advanced breast cancer patients selected for PIK3CA/AKT1 or PTEN mutations or PTEN loss." (PMID 31277699, 2019). "Taken together, the current study emphasized the potential of PIK3CA mutations as an important biomarker for breast cancer classification and the possible use of PIK3CA inhibitor as targeted therapy for breast cancer." (PMID 31404155, 2019). "This conclusion emphasized the need to assess the PIK3CA mutation status following trastuzumab therapy for breast cancer in order to predict disease progression." (PMID 31404155, 2019). "PIK3CA H1047R is a gain-of-function mutation located in the kinase region, and it is oncogenic and most common in breast cancer." (PMID 31781598, 2019). "Cancer-associated PIK3CA mutations occur frequently in breast cancer and are oncogenic in mammary epithelial cells and glands." (PMID 30999672, 2019). "MK-2206 monotherapy had limited clinical activity in advanced breast cancer patients selected for PIK3CA/AKT1 or PTEN mutations or PTEN loss." (PMID 31277699, 2019). "It is frequently amplified in endocrine resistant luminal breast cancers, rarely coincides with PIK3CA mutations, and is associated with poor prognosis." (PMID 31122207, 2019). "The Rap1 signaling pathway is the main target of the Damnacanthus indicus C.F.Gaertn, and we found three overlapping genes (MAP2K1, PIK3CA, and Raf1) in the Rap1 signaling pathway associated with the breast cancer." (PMID 30906409, 2019).
breast cancer (continued). "Further study indicated that the expression of CYP4Z1 and the pseudogene CYP4Z2P was associated with PIK3CA mutations in ERalpha-positive breast cancer." (PMID 30832689, 2019). "Previous research reported that PIK3CA mutations (exon 9 and/or exon 20) were detected in 45% of primary breast cancers." (PMID 31787861, 2019). "Two hotspot G-to-A mutations in exon 9 of the—often mutated in breast cancer—PIK3CA gene (E542K and E545K) are thought to be generated by APOBEC3B induced C-to-T (G-to-A) transitions." (PMID 31357602, 2019). "Activating somatic mutations in PIK3CA are considered early, initiating events in breast cancer, resulting in cell proliferation and resistance to apoptosis." (PMID 30813596, 2019). "PIK3CA mutations have been reported to be an early event in ER+ breast cancer and are found in more than 30% of ER+ primary treatment-naïve breast cancers." (PMID 31795152, 2019). "The high prevalence of mutated PIK3CA in breast cancer has created an active area of research as well as an attractive drug target." (PMID 30813596, 2019). "PIK3CA mutations are present in approximately 30% of all breast cancers, with a higher frequency reported in oestrogene or progesterone positive tumors as well as in HER2–positive breast cancers." (PMID 30795751, 2019). "The scientific rationale for this combination is based on the fact that mutations in the PIK3CA gene are frequently present (~ 30–40%) in breast cancer patients." (PMID 31852484, 2019). "Recently, an orally available PI3K alpha specific inhibitor termed Alpelisib has been approved for treatment of PIK3CA-mutated, hormone receptor-positive advanced breast cancer." (PMID 31665227, 2019). "Similar to breast cancer, the effect of PIK3CA mutational status on prognostic outcome remains controversial." (PMID 31905960, 2019). "The oncogene PIK3CA which is the one of most likely gain-of-function mutated in the breast cancer ranks in the second place by our method while in the 170th by Diffusion and 336th by Muf_max." (PMID 31088372, 2019). "For example, deletions in CDH1 and mutations in PIK3CA induce an immune subtype of breast cancer in a mice model." (PMID 31294536, 2019). "For example, in HER2-overexpressing breast cancer, mutations in PIK3CA have been shown to confer resistance to the HER2-targeted therapy, trastuzumab." (PMID 30813596, 2019). "In our study, the best response was observed in an AKT1 wild-type breast cancer patient who had an upstream PIK3CA mutation, which is in line with the finding of coincident PI3KCA mutations and improved PFS from another study." (PMID 31835495, 2019). "In breast cancer, tumors harboring PIK3CA mutations are often resistant to HER2-based therapy, and are less likely to achieve pathologic complete response to anti-HER2 treatments." (PMID 31635038, 2019). "ORR and 6 m PFS were both 5.6% (1/18), with one patient with HR+ breast cancer and a PIK3CA E542K mutation experiencing a partial response (on treatment for 36 weeks)." (PMID 31277699, 2019). "Recently, the Food and Drug Administration has granted approval for the PI3K inhibitor alpelisib for hormone receptor-positive, HER2-negative, PIK3CA-mutated breast cancer (in combination with fulvestrant)." (PMID 31404976, 2019). "PIK3CA is the most frequently mutated gene in human breast cancer, detected in 27% of breast carcinomas in the COSMIC database." (PMID 30813596, 2019).
breast cancer (continued). "A recent study evaluating 21,807 advanced cancers, in which 16% were breast tumours, showed the utility of the liquid biopsy to detect targetable mutations in breast cancer patients, for example, alterations in PIK3CA, ESR1 and MYC, FGFR1, HER2 amplifications." (PMID 30792813, 2019). "Of note, we were unable to identify any ER+ breast cancer cell line within the Cancer Cell Line Encyclopedia19 with both genomic loss/inactivating mutations in MAP3K1 coincident with a PIK3CA mutation." (PMID 31552290, 2019). "We therefore conducted this Phase II trial with the AKT Inhibitor MK-2206 in patients with advanced breast cancer who had tumors with a PIK3CA mutation or an AKT mutation and/or PTEN loss/PTEN mutation." (PMID 31277699, 2019). "PIK3CA mutations are found in approximately 35% of breast cancer patients, with C420R, E545K and H1047R being the most common variants." (PMID 30991934, 2019). "In our hands, however, breast cancer xenografts harboring the insulin-unresponsive, DR-resistant, PIK3CA-activating mutation H1047R remained largely sensitive to the anti-tumoral effects of metformin." (PMID 30984619, 2019). "Mutation rate in the PIK3CA gene (about 30%), instead, was in line with its expected frequency in breast cancer (cBioPortal)." (PMID 31216647, 2019). "The AKT1 mutation increases proliferation and tumor growth of breast cancer cells to an intermediate extent between wild type and PIK3CA mutated cells." (PMID 31752925, 2019). "PIK3CA is frequently mutated in breast cancer in three “hotspots”: E545K, E542K in exon 9 (helical domain) and H1047R in exon 20 (kinase domain)." (PMID 30754640, 2019). "Three of the breast cancer cell lines sensitive to a reduction in RNMT have oncogenic hotspot activating PIK3CA mutations; MCF7 expresses PIK3CA E545 K, T47D expresses PIK3CA H1047R, and JIMT-1 expresses PIK3CA C420R." (PMID 30991934, 2019). "Most commonly associated cancer varieties with PIK3CA mutation were endometrial cancer (uterine corpus) (52%) and breast carcinoma (33.6%)." (PMID 31905960, 2019). "Given that PIK3CA mutation is a relatively common mutation in breast cancer, we investigated the coexistence of these mutations." (PMID 29222734, 2018). "Of the 24 breast cancer patients with PIK3CA mutation‐positive metastasis, 92% were ER‐positive (n = 22), 8% were ER‐negative (n = 2), and 8% were HER2‐amplified (n = 2)." (PMID 29689598, 2018). "ddPCR demonstrated accurate detection of PIK3CA mutations in early stage breast cancer patients using ctDNA compared to tumor tissue with 93.3% sensitivity and 100% specificity." (PMID 30364656, 2018). "In one study, PIK3CA mutations were associated with the reduced efficacy of trastuzumab‐ and lapatinib‐based therapies in patients with breast cancer." (PMID 29325228, 2018). "There are 7 genes in this subnetwork, of which three genes (“GSK3B”, “CTNNB1”, “PIK3CA”) are associated with breast cancer." (PMID 30598085, 2018). "An analysis of The Cancer Genome Atlas (TCGA) data showed that PIK3CA was the most frequently mutated gene in breast cancer samples, second most frequently mutated gene in uterine corpus endometrial cancer and third most commonly mutated gene in HNSCC." (PMID 31093356, 2018). "PIK3CA mutation is a poor prognostic factor in HER2-positive breast cancer, and this finding was also confirmed in the CLEOPATRA trial." (PMID 29599915, 2018). "PIK3CA is the most frequent mutated gene in ER-positive early breast cancers, and PIK3CA mutation status is reported to affect activation of AKT and ERα." (PMID 29707142, 2018).
breast cancer (continued). "Its oncogenic function is underlined by the fact that the kinase domain mutated PIK3CA-H1047R induces mammary gland tumors in mouse knock-in models and colon carcinoma in a transgenic mouse model and the helicase mutated PIK3CA E545K mammary tumors." (PMID 30001368, 2018). "Recently, a large pooled analysis of more than 10,000 early-stage breast cancer patients reported that PIK3CA-mutated tumors are associated with a better prognosis." (PMID 30086764, 2018). "We therefore suggest that ERα activation, in addition to PIK3CA mutation, should be considered as a predictor of highly endocrine-responsive tumors and improved prognosis in postmenopausal ER-positive early breast cancer." (PMID 29707142, 2018). "We and others have previously reported disputed points concerning the use of ctDNA containing PIK3CA mutations as a biomarker in early‐stage breast cancer patients." (PMID 29689598, 2018). "In contrast, in early breast cancer, previous studies demonstrated that PIK3CA mutations were associated with a good prognosis in ER-positive, HER2-negative breast cancer." (PMID 29707142, 2018). "In a different study, PIK3CA mutations or low PTEN expression was associated with reduced progression‐free survival in trastuzumab‐treated patients with breast cancer." (PMID 29325228, 2018). "We next evaluated the genomic DNA of primary breast cancer specimens for PIK3CA mutations using the cobas® PIK3CA Mutation Test." (PMID 29707142, 2018). "PIK3CA mutations are seemingly the most common driver mutations in breast cancer with H1047R and E545K being the most common of these, accounting together for around 60% of all PIK3CA mutations and have promising therapeutic implications." (PMID 29523855, 2018). "High levels of mutated PIK3CA in serum DNA of breast cancer patients are associated with short progression-free and overall survival as compared to patients with low or no detectable amounts of mutated ctDNA." (PMID 30364656, 2018). "This is inconsistent with results from TCGA on breast cancer, which suggested the association between PIK3CA with ER positive expression." (PMID 30057548, 2018). "Regarding intrinsic breast cancer subtypes, mutations in PIK3CA were observed in 43–57% of Luminal A and in 31–35% of Luminal B carcinomas, respectively." (PMID 29273958, 2018). "The wild-type breast cancer cell lines transfected with constitutively oncogenic PIK3CA mutations showed almost insensitive toward trastuzumab, suggesting the major role of PIK3CA in the development of resistance to trastuzumab." (PMID 29942710, 2018). "The PIK3CA gene is mutated in ~36% of breast cancers reported in The Cancer Genome Atlas (TCGA) and the Catalogue of Somatic Mutations in Cancer (COSMIC) databases." (PMID 29636477, 2018).